INS (insulin)
Diseases named in the same sentence as INS in open-access papers (continued):
Sharing a sentence is not in itself a finding about the gene and the disease.
Hypoglycemia (continued). "Given their complementary mechanisms of action, insulin and GLP-1 RAs have been combined into fixed-ratio formulations to simplify treatment and enhance glycemic control while minimizing weight gain and the risk of hypoglycemia." (PMID 41531706, 2025). "6.If people experience hypoglycemia on neutral protamine Hagedorn (NPH) insulin or premixed insulins, conversion to analogue insulins may be of benefit (Grade 1C)." (PMID 41141497, 2025). "In studies where IDegAsp was used once or twice daily, total daily insulin dose adjustments were limited by concerns of hypoglycemia or rigidity in titration, which may also contribute to the lack of efficacy in certain T1DM populations." (PMID 41293743, 2025). "Conversely, insulin therapy in elderly patients with T2D requires careful consideration, as it may increase hypoglycemia-related cognitive risks." (PMID 41169480, 2025). "Similarly, in the comparison of insulin administration frequency (every 2 h versus continuous infusion), the evidence for hypoglycemia and hospital stay was also of very low certainty." (PMID 41227190, 2025). "However, when combined with insulin or SUs, the incidence rises to approximately 10%, underscoring the need for proper education on hypoglycemia prevention and management." (PMID 40607140, 2025). "Insulin use was also strongly correlated with an increased likelihood of hypoglycemia." (PMID 40162207, 2025). "In addition to inhibiting hepatic glucose production, glucagon also inhibits insulin secretion from pancreatic beta-cells, thereby ensuring that glucose is available during hypoglycemia." (PMID 41510436, 2025). "For example, the four trials utilized differing administration schedules and titration algorithms, which may have contributed to the differences in glycaemic control, body weight change, total insulin dose at end‐of‐study and hypoglycaemia." (PMID 40176458, 2025). "This pilot study did not include food intake or insulin delivery data, which restricted the ability to understand the cause of hypoglycemia episodes while driving." (PMID 40303943, 2025). "Notably, infected GRiKO mice exhibited increased glucagon levels, while insulin levels remained unchanged, indicating that the observed hypoglycemia is insulin-independent." (PMID 40702267, 2025). "As a result, nocturnal fasting hypoglycemia may occur, as insulin sensitivity tends to be highest between the hours of 2–4 a.m.." (PMID 40648766, 2025). "IDegLira also addresses two key barriers to insulin initiation: weight gain and hypoglycemia." (PMID 40958912, 2025). "A US public health surveillance study showed that older adults who received insulin were more than twice as likely as younger adults to visit the emergency department (ED) and nearly 5 times as likely to be hospitalized for insulin-related hypoglycemia." (PMID 40309264, 2025). "The regulation of RPE-derived insulin must be tightly controlled; excessive local insulin could theoretically induce localized hypoglycemia or promote aberrant vascular growth." (PMID 41301488, 2025). "Pathophysiologically, hypoglycemia is often related to excessive insulin secretion, which stimulates glucose uptake by insulin-dependent tissues (skeletal muscle and adipose tissue) and inhibits hepatic glucose production via glycogenolysis and gluconeogenesis." (PMID 40904956, 2025). "In our patient, the temporal correlation between methadone dose escalation and the onset of frequent hypoglycemic episodes was apparent, as evidenced by the reduction in insulin requirements and the increase in hypoglycemia frequency after methadone initiation." (PMID 41040769, 2025). "Insulin medication must be meticulously calibrated to prevent hypoglycemia, which might further impair respiratory function." (PMID 40142617, 2025). "Glucose is co-administered to prevent hypoglycemia; however, insulin alone may suffice in hyperglycemic patients." (PMID 40705102, 2025).
Hypoglycemia (continued). "The risk of hypoglycemia in advanced CKD is exacerbated by the failure of gluconeogenesis in the failed kidney as well as reduced clearance of many antihyperglycemic agents, particularly insulin." (PMID 40352967, 2025). "The majority of patients who experienced hypoglycemia were also receiving insulin at doses exceeding 0.4 units/kg/day and sulfonylureas, which likely contributed to the incidence of hypoglycemia observed during the study, while 63 patients (47%) did not experience any adverse effects." (PMID 40842739, 2025). "Although insulinoma is typically the primary suspicion, diminished insulin and C-peptide levels during hypoglycemia necessitate investigation for other etiologies, including insulin-like growth factor 2 (IGF-2)-secreting neoplasms like gastrointestinal stromal tumors (GISTs)." (PMID 41333493, 2025). "Future studies with focus of hypoglycemia follow-up, strict control over parameter ranges and dose titration methods, and better evaluation of effectiveness combination of insulin and liraglutide may be considered." (PMID 40469149, 2025). "Early devices operated to suspend insulin delivery at predefined thresholds, but newer systems enable modulation of basal insulin dosing in response to real-time glucose trends and even incorporate glucagon to prevent hypoglycaemia." (PMID 40718205, 2025). "Similar to incretins and GLP-1 receptor agonists, betagenin does not stimulate insulin secretion when the circulating glucose concentration is low, thereby reducing the risk of hypoglycemia." (PMID 39826690, 2025). "This raised a strong suspicion of hypoglycemia due to non–insulin‐mediated mechanisms." (PMID 40697895, 2025). "Dipeptidyl peptidase (DPP-4) inhibitors prolong the action of incretins, improving insulin secretion without increasing the risk of hypoglycemia." (PMID 40649704, 2025). "Diabetic patients may also be at risk, as some coumarins modulate glucose metabolism, potentially leading to hypoglycemia when co-administered with metformin or insulin." (PMID 40430886, 2025). "Blood glucose improved, allowing for a transition to long-acting insulin (Lantus), premeal insulin (Admelog), and an insulin sliding scale, which was transitioned to Admelog toward the end of admission due to intermittent episodes of hypoglycemia." (PMID 40671975, 2025). "Similarly, the conversion from human to analogous insulin enabled better glycemic control and reduction of hypoglycemia events." (PMID 40303934, 2025). "Notable findings of lab values were markedly elevated liver function tests, indicating hepatocellular injury, severe coagulopathy, lactic acidosis, hypoglycemia with low insulin levels, and significant neurologic injury due to elevated neurofilament light chain." (PMID 41458770, 2025). "As a result of falsely elevated blood glucose readings, excessive insulin treatment may lead to iatrogenic hypoglycemia." (PMID 40430224, 2025). "Additionally, exercise-induced hypoglycemia can be challenging to prevent solely by reducing insulin doses, but adding glucagon has shown potential." (PMID 40231429, 2025). "Moreover, a significant increase in nocturnal hypoglycemia was observed for both level 1 and level 2 events with once‐weekly insulin." (PMID 40186384, 2025). "Therefore, health education for patients living with T1D on insulin administration and the detection and management of hypoglycemia symptoms at home is necessary." (PMID 40110390, 2025). "Euglycemic DKA should be promptly treated with isotonic fluids such as lactated ringers with the addition of dextrose 5% or 10% if hypoglycemia persists, an insulin drip at the rate of 0.1 units/kg/hour or 0.05 units/kg/hour, and supplemental intravenous potassium." (PMID 40357083, 2025). "The test for anti-insulin antibodies was negative, and the other potential causes of hypoglycemia, such as adrenal insufficiency, were ruled out, strongly suggesting insulinoma." (PMID 40405975, 2025).
Hypoglycemia (continued). "Insulinomas produce excess insulin, leading to hypoglycemia." (PMID 40144450, 2025). "Another major unresolved issue is the premature insulin release under hypo-/normoglycemic conditions, as many PBA-based microgels begin to swell at low glucose concentrations, increasing the risk of hypoglycemia." (PMID 40807234, 2025). "This sudden surge of bioactive insulin, in turn, triggers hypoglycemia." (PMID 41585798, 2025). "This may be due to fear of disease severity, injection-related anxieties, fear of hypoglycemia, and lifestyle disruption, as all activities, such as meal planning and exercise, must be coordinated with insulin use." (PMID 41523497, 2025). "C-peptide and insulin were checked twice during an episode of hypoglycaemia." (PMID 39931615, 2025). "Successful management of euDKA is challenging since a sufficient insulin dose must be given to allow for adequate clearance of ketones while dextrose-containing fluids must be concurrently administered at appropriate rates to prevent hypoglycemia." (PMID 40900206, 2025). "The risk of hypoglycemia with dual agonists remains relatively low, particularlyin the absence of concomitant insulin or insulin secretagogues." (PMID 40776973, 2025). "Other adverse reactions documented with metreleptin include, but are not limited to, hypersensitivity reactions (as reported for Case 10), acute pancreatitis following discontinuation of metreleptin, and hypoglycemia with concomitant use of insulin and other glucose-lowering agents." (PMID 40842493, 2025). "A more recent case report described a 61-year-old diabetic patient who developed a focal seizure of temporal origin due to insulin-induced hypoglycemia at 46 mg/dL, with clear EEG documentation showing 5–6 Hz rhythmic slow waves involving the right temporal region." (PMID 40656454, 2025). "Overestimation of the amount of avCHO in a low-carb food may be a concern for people with type 1 diabetes (T1D) who might overestimate the amount insulin required, possibly leading to hypoglycemia." (PMID 41439105, 2025). "The diagnostic investigations included a fasting test that revealed severe hypoglycemia (36 mg/dl) after 12 h, in combination with elevated ketone body levels (3.1 mmol/L), suppressed insulin levels, normal adrenal cortex response, normal ammonia levels, and no metabolic acidosis." (PMID 40866742, 2025). "Our results indicate that the insulin assay conducted on the Siemens Atellica platform could be used to diagnose factitious hypoglycemia by detecting the specific insulin analogs involved." (PMID 39030378, 2025). "In some cases, hypoglycemia, excessive glucose fluctuations, and weight gain may also occur with intensive insulin therapy." (PMID 41012462, 2025). "Therefore, the study’s findings suggested that patients with a low level of knowledge regarding insulin self-administration were 4.87 times more likely to develop hypoglycemia compared to patients with good knowledge (AOR=4.87; 95% CI: 1.55-15.26)." (PMID 40110390, 2025). "Our patient showed typical hypoglycemia symptoms after taking insulin while he was fasting." (PMID 41024163, 2025). "However, many patients are still reluctant to initiate or adhere to insulin therapy due to reasons which include the fear of addiction, injection, side effects such as hypoglycemia and weight gain, inconvenience, and social stigma." (PMID 40242444, 2025). "Experimental studies in rodents have shown that glucose infusion worsens neuronal death in insulin-induced hypoglycemia by increasing superoxide production, suggestive of therapeutic administration of uncontrolled glucose delivery proving to be detrimental by worsening the initial neuronal injury." (PMID 40119223, 2025). "However, precise carbohydrate monitoring is essential to avoid hypoglycemia, as excess insulin release can occur when carbohydrate intake is insufficient to match insulin secretion." (PMID 39859337, 2025).
Hypoglycemia (continued). "After meal ingestion, the release of SS-28 from the stomach prevents the occurrence of hypoglycemia and may mitigate potential reductions in tissue insulin sensitivity." (PMID 40427747, 2025). "FFA1 is known to stimulate pancreatic β-cells to secrete insulin, which could explain its possible link to hypoglycemia." (PMID 41282005, 2025). "What is novel from the current study is that when compared to controls, exposure to insulin-induced hypoglycemia resulted in even higher epinephrine release in the female Abx group, while the ability to respond to hypoglycemia in male Abx offspring was significantly reduced." (PMID 40693139, 2025). "The reasons for non-adherence varied: 8% of patients in the insulin therapy group cited hypoglycemia risk, 7% reported injection discomfort, and 3% mentioned forgetfulness." (PMID 40959330, 2025). "Furthermore, rapid hypoglycemia is less likely to occur with subcutaneous insulin administration than with intravenous insulin administration." (PMID 38905235, 2024). "These tumors result in excessive insulin production, culminating in hypoglycemia." (PMID 38595852, 2024). "Safety endpoints included any adverse events, such as serious and severe adverse events, events probably and possibly related to insulin use, hypersensitivity, injection-site reactions, hypoglycemia (overall, combined clinically relevant and severe, and nocturnal), and weight gain." (PMID 39200316, 2024). "Role in Glucose Homeostasis: Glucagon, a hormone produced by pancreatic alpha cells, counterbalances insulin effects by stimulating hepatic glucose production through glycogenolysis and gluconeogenesis, raising blood glucose levels during fasting states or hypoglycemia." (PMID 39126081, 2024). "This may be partly due to the fact that diabetic rats treated with insulin to control their blood glucose during experimentation may undergo multiple episodes of undocumented antecedent hypoglycaemia before the HAAF protocol begins." (PMID 38392992, 2024). "This allows the athlete to start the event with low circulating insulin levels, which may be advantageous in endurance events and for individuals prone to hypoglycemia." (PMID 38542818, 2024). "Males, more than females, show fasting hypoglycemia and increased insulin sensitivity." (PMID 38519536, 2024). "At a dose of 12 mg kg−1, AZD7762 treatment did not cause hypoglycemia at 0 min, while still significantly improving glucose tolerance and insulin secretion at both 0- and 15-min postglucose injection." (PMID 37945898, 2024). "Although insulin therapy is the best treatment option for T1DM patients, chronic insulinization may cause hypoglycemia episodes, increased body weight gain and increased oxidative stress that results in endothelial dysfunction and inflammation." (PMID 38892513, 2024). "Recurrent hypoglycemia, as reported in a case series, may result from the voluntary administration of extra insulin, with the purpose of consuming more carbohydrates or seeking attention." (PMID 39334618, 2024). "We hypothesized that treatment with an SSTR2 antagonist (PRL-2903), prior to insulin-induced hypoglycemia, would increase the glucagon response to iatrogenic (i.e., insulin-induced) hypoglycemia." (PMID 38510652, 2024). "Moderate hypoglycemia days were significantly decreased in those using a hospital-managed insulin pump (3.1%) and a caregiver-managed home insulin pump (4.5%) compared with those receiving insulin injections (5.1%)." (PMID 38324312, 2024). "Two additional patients who developed hypoglycemia involved co-administration of insulin." (PMID 38861153, 2024). "Biochemical investigations revealed a hypoglycemia of 41 mg/dL, respectively 46 mg/dL, a plasma insulin level of 15.28 uIU/mL, respectively 15.48 uIU/mL (normal value: 3–25 uIU/mL), and C-peptide of 2.2 ng/mL (normal value: 0.9–7.1 ng/mL), respectively 2.01 ng/mL, in two consecutive days." (PMID 38791571, 2024).
Hypoglycemia (continued). "Exercise enhances insulin sensitivity and improves overall health, but it requires careful planning to avoid hypoglycemia.Diet: Nutritional management focuses on achieving a balanced intake of carbohydrates, proteins, and fats, along with adequate vitamins and minerals." (PMID 39310514, 2024). "These devices also reduced hypoglycemia in insulin-requiring DM patients." (PMID 39149659, 2024). "This is followed by an exaggerated second phase insulin release and subsequent hypoglycaemia." (PMID 38370356, 2024). "Similarly, insulin use has revealed odds of 1.88, meaning that there is 88% increase in the odds of hypoglycemia for individuals receiving insulin (P = 0.015)." (PMID 39208059, 2024). "Three studies describe the use of newer glucagon formulations in insulin-induced hypoglycemia." (PMID 39944479, 2024). "The investigators concluded that MDG with or without reduction in insulin basal rate appeared to decrease exercise-associated hypoglycemia in adults with T1D." (PMID 39944479, 2024). "Finally, we did not compare the differences between the two interventions in terms of insulin dose, nocturnal hypoglycemia, or the number of repeated hypoglycemia in the same individual, because few relevant data were reported in most trials." (PMID 39629047, 2024). "Blood insulin and glucagon concentrations, which play a major role in regulating blood glucose levels, were compared pre- and postoperatively to examine the physiological responses to hypoglycemia." (PMID 38393097, 2024). "Moreover, the incidence of severe hypoglycemia was lower with once-weekly insulin icodec compared to once-daily degludec (RR 0.00016 [95% CI 0 to 0.41])." (PMID 38172995, 2024). "At the time, the CGM devices used in this study were all early generation; they were larger than current devices, and they required fingerstick calibrations in addition to fingerstick glucose checks for any treatment decisions, including insulin dosing or treating hypoglycemia." (PMID 39306610, 2024). "CSII might be helpful in reducing the incidence of hypoglycemia with regard to the advantage of reducing insulin dosage." (PMID 38664886, 2024). "This reduces tumor cell proliferation and insulin secretion, alleviating hypoglycemia." (PMID 39723310, 2024). "Excess weight gain may also occur over time due to intensive insulin therapy, inadequate exercise, and excess food intake, often in defense against hypoglycemia." (PMID 39605938, 2024). "In this hypothesis, insulin secretion from β-cells decreases during hypoglycemia and, at the same time, serves as an activating signal for the release of glucagon from α-cells." (PMID 38397994, 2024). "However, intensive insulin therapy increased the number of hypoglycemia events, including life-threatening, severe hypoglycemic events." (PMID 38786050, 2024). "For patients receiving injectable insulin, dental appointments should be scheduled so as not to interfere with maximal insulin activity because the risk of hypoglycemia is maximized during this period." (PMID 38344477, 2024). "Taken together, our data support the hypothesis that dysregulation of serotonin metabolism, with reduction in fasting levels and increased meal-stimulated levels, may contribute to excessive prandial insulin secretion and hypoglycemia in patients with PBH." (PMID 39264731, 2024). "Tight glucose control has been linked to increased hypoglycemia rates and increased delirium rates, which may be due to the fact that insulin-induced hypoglycemia affects brain function." (PMID 38966222, 2024). "Therefore, we studied young DNAJC3 K.O. mice, less than 8 weeks of age, equivalent to human infancy, to investigate insulin release, glucose homeostasis, and evidence of hypoglycemia." (PMID 38279270, 2024). "Hypoglycemia episodes increase with insulin secretagogues, which may explain the larger HSUV decrement in Marrett’s study where 50% of study subjects were on sulphonylureas." (PMID 38574169, 2024).